ENSG00000293662 (novel protein similar to embryonic testis differentiation homolog A)
Gene: Protein-coding gene on chromosome X (135,305,788 to 135,306,402, reverse strand). Ensembl gene ENSG00000293662.
Homologues: Orthologues: mouse 1600025M17Rik (35% identical). Paralogues in human: SMIM10L2B-AS1 (72% identical).